ICAM1 (intercellular adhesion molecule 1)
Diseases named in the same sentence as ICAM1 in open-access papers (continued):
Sharing a sentence is not in itself a finding about the gene and the disease.
Hyperglycemia (continued). "In the presence of risk factors such as DM (hyperglycaemia), endothelial cells are activated to express adhesion molecules such as vascular cell adhesion molecule-1 (VCAM-1) and intercellular adhesion molecule-1 (ICAM-1) which are required for leukocyte adhesion to the endothelial surface." (PMID 22347666, 2012). "Hyperglycemia could also increase the expression of ICAM-1, VCAM-1, and MCP-1 release." (PMID 22474415, 2012). "Other studies link inflammatory agents, adipokines, and cell adhesion molecules—such as intercellular adhesion molecule 1 (ICAM-1) or vascular cell adhesion molecule 1 (VCAM-1)—with insulin resistance and hyperglycemia during pregnancy." (PMID 40362828, 2025). "Hyperglycemia, which leads to the expression of ICAM1 by EC, promoted monocyte adhesion to the endothelial bed while GSNO treatment abrogated hyperglycemia-induced attachment of monocytes to EC." (PMID 40289112, 2025). "Hyperglycemia induces adhesive molecules like VCAM-1 and ICAM-1, which contribute to damage in the retina, the neuro-vascular coupling tissue." (PMID 39635433, 2024). "To study the impact of hyperglycemia and aging on HUVEC tubule function, we added another marker of vascular injury, vWF, ICAM-1, and performed tubular studies." (PMID 38540749, 2024). "TNF-α and hyperglycemia have been reported to elevate plasminogen activator inhibitor-1 (PAI-1) and ICAM-1 and VCAM-1 expression in endothelial cells." (PMID 37367894, 2023). "Similar to other studies, our study showed that hyperglycemia increased the expression of VCAM-1, ICAM-1, and VEGF-1 in HUVEC cells." (PMID 36982499, 2023). "However, the relations between VEGF, ICAM1 and L/Zi under high hyperglycemia remain unclear." (PMID 28738845, 2017). "High-fat diet-induced hyperglycemia is a factor which is recognized to alleviate the level of VEGF and ICAM-1." (PMID 28738845, 2017). "Meanwhile, hyperglycemia increased the mRNA and protein expression of ICAM-1 and iNOS, while PARP-1 deletion reduced hyperglycemia-induced ICAM and iNOS expression." (PMID 27027354, 2016). "Our present study showed that hyperglycemia induced by STZ increased the expression of inflammatory molecules, such as ICAM-1 and VCAM-1, in the aorta, which was suppressed by ipragliflozin treatment." (PMID 27833913, 2016). "T2D patients showed increased ICAM-1 and VCAM-1 plasma concentrations, which was thought to be related to hyperglycaemia." (PMID 26529237, 2015). "In Müller cells exposed to hyperglycaemia, the protein levels of MCP-1, soluble ICAM-1, CCL20, growth-regulated oncogene/cytokine-induced neutrophil chemoattractant-1 (GRO/CINC-1), VEGF and IL-6 were increased compared to normoglycaemic controls." (PMID 26222724, 2015). "Many studies indicated that NF-κB signal pathway was involved in the hyperglycemia-mediated up-regulation of gene and protein expression of endothelial adhesion molecules, including VCAM-1, ICAM-1, and E-selectin." (PMID 23311470, 2013). "On the other hand, the CAG combination exhibited a highly significant decrease of both hyperglycaemia- and 3,4-DGE-induced ICAM-1 expression." (PMID 22045866, 2012). "Intermittent hyperglycaemia increases oxidative stress‐related cell apoptosis in vascular endothelial cells through PKC‐dependent activation of NAD(P)H oxidase and the expression of several adhesion molecules, such as ICAM‐1, VCAM‐1, and E‐selectin." (PMID 40049179, 2025). "Furthermore, ELA administration attenuated adhesive molecules ICAM-1 and VCAM-1 expression under hyperglycemia." (PMID 37540330, 2023). "Therefore, we aimed to analyze the effects of JMJD1A on inflammatory proteins including IL-6, IL-8, ICAM-1, and MCP-1 under hyperglycemia and hypoxic stimulation of HUVECs." (PMID 34479471, 2021). "In studies using umbilical vein endothelial cells, fluctuant hyperglycemia could significantly increase the content of IL-6, TNF-α and ICAM-1 in vitro." (PMID 27496150, 2016).
Hyperglycemia (continued). "The Mediterranean diet also reduced the negative effects of acute hyperglycemia, induced by a hyperglycemic clamp, on endothelial function, nitrotyrosine, 8-iso-PGF2a, IL-6 and ICAM-1 levels." (PMID 25407792, 2014). "The molecular mechanism by which hyperglycemia further enhances the expression of ICAM-1 is not fully understood." (PMID 25389378, 2014).
asthma (80 papers, 2006 to 2025). "ICAM1 plays an important role in the inflammatory response, with some SNPs of ICAM1 found to be associated with asthma." (PMID 39769348, 2024). "A case-control study conducted in preschool wheezers prospectively followed until six years of age found that intercellular adhesion molecule 1 (ICAM-1) SNP rs5498 was positively associated with asthma development." (PMID 36362786, 2022). "Upregulation of ICAM-1 in epithelial and endothelial cells is believed to be a hallmark of asthma in adults." (PMID 20953388, 2011). "Asthma model mice and ICAM-1 deficient mice challenged intranasally with IL-33." (PMID 37947634, 2023). "ICAM-1 has long been known to mediate cell-to-cell contacts in antigen presentation and intra- and extracellular signaling pathways, and it has been linked to asthma." (PMID 38140051, 2023). "Acupoint catgut embedding reduces EOS aggregation and promotes its regulation to alleviate the airway inflammatory response in the episode of asthma, which might be associated with the inhibition of p38MAP, ICAM-1, and IL-4 mRNA expression." (PMID 37740212, 2023). "It is important to note that soluble ICAM-1 (sICAM-1) in the sera is linked with asthma severity, suggesting that ICAM-1 may represent an adequate target for the treatment of the disease." (PMID 33193309, 2020). "Overexpressed CD44 could further induce the expression of asthma-associated molecules, including IL-6, IL-8 and intercellular adhesion molecule 1 (ICAM), which promote progression of asthma." (PMID 29471827, 2018). "TNF-α increases the expression of ICAM-1 and other adhesion molecules on a number of different cell types, and it is associated with wheezing illnesses in infancy and the development of the late-phase allergic reactions and asthma." (PMID 22966430, 2012). "Tnfr2–/– mice were unable to upregulate ICAM1, induce leukocyte influx into the lung, and generate the asthma phenotype." (PMID 40526428, 2025). "This study leveraged the characteristic increase in Intercellular Adhesion Molecule-1 (ICAM-1) expression in AECs under conditions of asthma inflammatory stimulation in order to enhance the specific delivery efficiency of siRNA into AECs." (PMID 39928241, 2025). "The following adhesion molecules play a key role in cell transmigration and activation in asthma: intercellular adhesion molecule 1 (ICAM-1), VCAM-1, and its ligand VLA-4." (PMID 39703514, 2024). "Several subsequent studies further validated the potential link between ICAM-1 expression and asthma pathogenesis." (PMID 35316427, 2022). "The expression of ICAM-1 is known to be elevated in asthma, and this favors the binding of ICAM-1-positive cells to LFA-expressing cells." (PMID 35316427, 2022). "Rhinoviruses use ICAM-1 molecule (over-expressed within asthma patients with allergic airways), but SARS-CoV-2 uses angiotensin-converting enzyme 2 (ACE2) and transmembrane protease serine 2 (TMPRSS2) receptors." (PMID 35756853, 2022). "In our previous work, we have shown that the airway epithelial defect in asthma is closely associated with abnormal expression of epithelial adhesion molecules such as CTNNAL-1, ICAM-1 and integrin-β4 50-52." (PMID 35173551, 2022). "As for the receptor of virus, the expression of ICAM-1 is upregulates in asthma and its expression further increases after RV infection, which can induce the eosinophilic airway inflammation." (PMID 35795686, 2022). "In asthma, ICAM-1 mainly regulates the adhesion between cells and increases adhesion between inflammatory cells and airway epithelial cells." (PMID 33628113, 2021). "Prior studies have focused on the function of LFA-1 and ICAM-1/2 In the context of ILC2-dependent asthma, but the exact contributions of LFA-1, ICAM-1, and ICAM-2 in the context of ILC2 trafficking and transmigration to the lungs remains elusive." (PMID 33193309, 2020).
asthma (continued). "In this study, we demonstrate that ILC2 expression of adhesion molecules LFA-1 and ICAM-1 play crucial roles in the development of IL-33-induced asthma symptoms, albeit at different levels." (PMID 33193309, 2020). "Of note, ICAM1 has been indicated to be increased by RV infection and identified to be a target for the development of therapeutic interventions for virus-induced asthma exacerbation." (PMID 32849329, 2020). "In the context of asthma, anti-LFA-1 and anti-ICAM-1 were shown long ago to be beneficial in experimental asthma through effects on CD4+ T-cells." (PMID 33193309, 2020). "Abnormal cell surface ICAM-1 expression status and soluble ICAM-1 level are related to the pathogenesis of some clinical diseases (e.g. multiple sclerosis, asthma, rhinitis etc)." (PMID 30473535, 2018). "The expression levels of the classical inflammatory biomarkers such as IgG, IgE, MMP9, IFN-γ, IL-4, and ICAM-1 that play an important role in the pathogenesis of asthma were also assessed." (PMID 28050193, 2016). "The upregulation of ICAM‐1 expression in airway epithelial cells has been previously reported in asthma patients and monkeys that were stimulated by antigen inhalation 12, 13, 37 and have been associated with airway hyperresponsiveness." (PMID 27957326, 2016). "Based on these findings, we hypothesized that increased levels of ICAM‐1 expression may result in increased RV replication and infection‐induced cytokine production and that these effects may be associated with increased airway inflammation and subsequent asthma exacerbation." (PMID 27957326, 2016). "Previous reports have found that ICAM1 induction during inflammation enhances eosinophil survival by activating cellular signaling mechanisms, resulting in eosinophilia in asthma." (PMID 25879517, 2015). "We have shown for the first time a major group allergen-induced asthma exacerbation model and the possible use of a domain-specific anti-ICAM-1 antibody as possible treatment for rhinoviral triggered exacerbations of asthma." (PMID 23935498, 2013). "Several studies have demonstrated that ICAM-1 is upregulated during inflammation, asthma, rheumatoid arthritis and lung injury, and the expression of ICAM-1 is mediated by various inflammatory cytokines, particularly TNF-α." (PMID 24137303, 2013). "VCAM-1 and ICAM-1 expression is known to be increased in the bronchial epithelium of asthma patients, and these cell adhesion molecules have been shown to be related to the release of eosinophil cationic protein." (PMID 23855490, 2013). "Eosinophils accumulate at innervating cholinergic nerves in asthma and adhere to nerve cells via intercellular adhesion molecule-1 (ICAM-1)." (PMID 21686182, 2011). "Our study is similar to previous reports and consistent with reports of increased ICAM-1 expression in the lungs of patients with asthma." (PMID 20953388, 2011). "There is a close correlation between high concentration of sICAM-1 and high expression of ICAM-1 with the severity of asthma in patients and asthmatic rats." (PMID 20953388, 2011). "RN strongly inhibited the increased expression of ICAM-1 and HO-1 following the induction of asthma (P < .05) when compared with model control rats." (PMID 20953388, 2011). "ICAM-1 and its soluble form, sICAM-1, play important roles in the development of airway/lung inflammation in asthma." (PMID 20953388, 2011). "IFN-γ has many proinflammatory effects and has been shown to play an important role in early childhood asthma through the upregulation of ICAM-1 and the cellular receptor for TNF-α." (PMID 16952309, 2006). "The protein expression of nuclear factor‐kappa B (NF‐κB) inhibitor (IκBa) was increased in the ATRA group than asthma group, whereas the expression of NF‐κB and intercellular adhesion molecule 1 (ICAM‐1) was reduced in the ATRA group relative to the asthma group." (PMID 39466149, 2024).
asthma (continued). "Furthermore, the cytokines regulated by NF‐κB, including IL‐1β, IL‐2, ICAM‐1, and VCAM‐1 are associated with obese asthma." (PMID 38286741, 2024). "In this context, eosinophils adhering to ICAM-1 can exacerbate asthma symptoms." (PMID 39518415, 2024). "Further study of ICAM-1 regulation in neutrophils during asthma is warranted given the critical role that ICAM-1 plays as a receptor for adhesion for a subset of rhinoviruses and thus facilitates entry and may propagate disease." (PMID 38534377, 2024). "ICAM-1 is involved in eosinophil transmigration through the vascular endothelium, leading to their accumulation in asthmatic airways, a key feature of chronic and severe asthma." (PMID 39518415, 2024). "Interestingly, neutrophils isolated from the peripheral blood of asthma patients seen in the ER with mild-to-moderate exacerbations expressed the greatest amount of ICAM-1." (PMID 38534377, 2024). "Using the flow cytometry of freshly isolated neutrophils, we found a trend towards increased ICAM-1 expression on neutrophils from patients with severe acute asthma exacerbations as compared with healthy donors, though the difference was not statistically significant." (PMID 38534377, 2024). "In addition, our previous OVA-induced asthma study revealed that increased adhesion molecules, such as ICAM-1 and VCAM-1, were found to influx inflammatory cells from the blood into the lungs." (PMID 35163544, 2022). "In addition, because ICAM-1 serves as a receptor for RV, an ICAM-1 blocker was studied for its ability to reduce RV-infection-induced acute asthma exacerbations." (PMID 36077310, 2022). "The expressions of inflammatory cytokines, MUC5AC and ICAM-1 were determined by quantitative reverse transcription PCR (RT-qPCR), enzyme-linked immunosorbent assay (ELISA) and Western blot after TXL was exposed to an in vitro asthma model." (PMID 35000533, 2022). "Nevertheless, the potential role of ICAM-1 in asthma is now widely accepted, so the development of therapeutic approaches targeting these proteins may well be beneficial to reduced inflammation, AHR and asthma exacerbations." (PMID 35316427, 2022). "The role of ICAM-1 in asthma has been extensively studied since the 1990s." (PMID 35316427, 2022). "Rhinovirus was shown to elevate the expression of ICAM-1 in human airway smooth muscle cells, which may play a role in virus-induced asthma exacerbations." (PMID 31293985, 2019). "One possible mechanism underlying aggravation of asthma by SO2 could be that SO2 derivatives increase the expression levels of EGF, EGFR, ICAM-1, and COX-2 proteins in BEP2D cells." (PMID 30885130, 2019). "In addition, inhibition of cAMP signalling by DDA significantly reduced RV induced ICAM1 expression in asthma and control cells." (PMID 29182620, 2017). "Inhibitors of MMPs regulate inflammatory cell migration by reducing ICAM-1 expression in asthma." (PMID 26783416, 2016). "The relationship between viral infection and asthma exacerbation may be explained by TLR or ICAM-1, but a higher incidence of smoking may affect viral infection in asthmatic patients in clinical practice." (PMID 25901797, 2015). "ICAM1 plays a dominant role in allergic rhinitis and asthma." (PMID 24995349, 2014). "The two studied ICAM1 SNPs were associated with childhood asthma among children exposed to ETS, but not among those without ETS exposure (p of interaction = 0.05 and 0.01 for rs5491 and rs5498, respectively)." (PMID 25003170, 2014). "Chronic antigen challenge has been shown to increase ICAM-1 expression in the airway epithelium, which may be related to airway inflammation in asthma." (PMID 22966430, 2012). "Inflammatory conditions such as asthma, in which ICAM-1 expression is increased on the respiratory epithelial surfaces, may cause a predisposition to RV infection because ICAM-1 is a receptor for the major group of RVs." (PMID 22966430, 2012).
asthma (continued). "Therefore, it is likely that eosinophil adhesion to epithelial cells through ICAM-1 would be enhanced during RV-induced asthma exacerbation." (PMID 22004287, 2011). "ICAM-1, which acts as a primary adhesion site for the HRV, could be effectively blocked to prevent viral-binding to host cells, thus preventing viral-induced infections and associated pathology in patients with COPD/asthma (as well as IPF etc.)." (PMID 35316427, 2022). "Although the reason for lower replication in the asthma group is unclear, we speculate that use of inhaled or oral corticosteroids by the subjects with asthma could have suppressed ICAM-1 expression, and that this suppression may have persisted through several cell generations in tissue culture." (PMID 24219422, 2013). "Since both IP-10 and ICAM-1 can be upregulated in RV-induced asthma exacerbation our results indicate that IP-10 interaction with ICAM-1 in the airway may play an important role in the activation and infiltration of eosinophils during RV-induced asthma exacerbation." (PMID 22004287, 2011). "Intercellular adhesion molecule-1 (ICAM-1) and vascular cell adhesion molecule-1 (VCAM-1) are markers of inflammatory responses involved in various diseases, including asthma and rheumatoid arthritis." (PMID 37228610, 2023). "The levels of TNF-α, TNFR2, and CCL-9 in the asthma model group increase, while the levels of IFN-γ, IL-1α, ICAM-1, and IL-4 increased in the Majie cataplasm group, especially IFN-γ and IL-1α." (PMID 35600943, 2022). "Specifically, the high-dose MaR1 treatment significantly reduced the ICAM-1 and COX-2 mRNA expression levels in the OVA-induced asthma mice." (PMID 33628113, 2021). "Activation markers, such as integrin Mac-1 (CD11b/CD18), L-selectin (CD62L), CBRM1/5, ICAM-1 (CD54), PD-L1 (CD274), PSGL-1 (CD162), FcγRII (CD32), CD16, CD44, and CD69, were shown to be upregulated on circulating or sputum granulocytes from asthma patients." (PMID 32731346, 2020). "In conclusion, modulation of LFA-1 and/or ICAM-1 represents a promising and unappreciated novel therapeutic strategy regulating trafficking and cytokine production respectively in ILC2-dependent asthma." (PMID 33193309, 2020). "Both ICAM1 and ETS, and interactions between these two factors are likely to be involved in the development of asthma in childhood." (PMID 25003170, 2014). "Previous studies have found higher levels of circulating adhesion molecules in COPD patients and having high levels of ICAM-1 and VCAM-1 was related to higher airway resistance in asthma in one study." (PMID 23924044, 2013). "There is an increasing evidence that inflammatory proteins, such as VCAM-1, ICAM-1, cPLA2, COX-2, and MMP-9 are involved in the pathogenesis of respiratory diseases, such as asthma and COPD." (PMID 23690670, 2013). "According to previous studies, ICAM-1 and VCAM-1 are upregulated on the bronchial vascular endothelium after bronchial allergen challenge in patients with asthma." (PMID 23029210, 2012). "One clinical trial showed that experimental infection with HRV-16 (an HRV-A species) in asthma patients increased intercellular adhesion molecule-1 expression in the bronchial epithelium regardless of ICS treatment." (PMID 38053068, 2023). "In addition, immunohistochemistry revealed increased ICAM-1 and VCAM-1 expression in vessels in the lung tissues in mice with both ampicillin-treated D. farinae and untreated D. farinae-induced asthma." (PMID 37252681, 2023). "In addition, it significantly reduced the HRV-induced ICAM-1 expression, the main adhesion site for both HRV type A and B, in BECs of asthma and COPD patients." (PMID 36479289, 2022). "Furthermore, high-dose MaR1 treatment markedly suppressed the activation of the NF-κB signaling pathway, the degradation of IκBα, and the expression of inflammatory genes downstream of NF-κB, such as COX-2 and ICAM-1, in the OVA-induced asthma mouse model." (PMID 33628113, 2021).